DCP2 (decapping mRNA 2)
Description:
Decapping metalloenzyme that catalyzes the cleavage of the cap structure on mRNAs. Removes the 7-methyl guanine cap structure from mRNA molecules, yielding a 5'-phosphorylated mRNA fragment and 7m-GDP. Necessary for the degradation of mRNAs, both in normal mRNA turnover and in nonsense-mediated mRNA decay. Plays a role in replication-dependent histone mRNA degradation. Has higher activity towards mRNAs that lack a poly(A) tail. Has no activity towards a cap structure lacking an RNA moiety. The presence of a N(6)-methyladenosine methylation at the second transcribed position of mRNAs (N(6),2'-O-dimethyladenosine cap; m6A(m)) provides resistance to DCP2-mediated decapping. Blocks autophagy in nutrient-rich conditions by repressing the expression of ATG-related genes through degradation of their transcripts.
Synonyms: NUDT20
Tractability: Small molecule: a structure with a bound ligand is known. PROTAC: ubiquitination databases record sites on it; its protein half-life has been measured.
Gene: Protein-coding gene on chromosome 5 (112,976,702 to 113,022,195, forward strand). Ensembl gene ENSG00000172795.
Subcellular location: Cytoplasm, P-body; Nucleus
Subcellular location (Human Protein Atlas): Cytoplasmic bodies; Nucleoplasm; Cell Junctions
Pathways (Reactome):
Metabolism of RNA: Butyrate Response Factor 1 (BRF1) binds and destabilizes mRNA; KSRP (KHSRP) binds and destabilizes mRNA; Tristetraprolin (TTP, ZFP36) binds and destabilizes mRNA; mRNA decay by 5' to 3' exoribonuclease
Cellular responses to stimuli: ATF4 activates genes in response to endoplasmic reticulum stress
Gene Ontology:
Molecular function: 5'-(N(7)-methylguanosine 5'-triphospho)-[mRNA] hydrolase activity; 5'-3' RNA exonuclease activity; protein binding; telomerase RNA binding; RNA exonuclease activity, producing 5'-phosphomonoesters; hydrolase activity; manganese ion binding; RNA binding
Biological process: histone mRNA catabolic process; mRNA catabolic process; negative regulation of telomere maintenance via telomerase; regulation of mRNA stability; regulation of telomerase RNA localization to Cajal body; deadenylation-dependent decapping of nuclear-transcribed mRNA; nuclear-transcribed mRNA catabolic process, deadenylation-dependent decay; nuclear-transcribed mRNA catabolic process, nonsense-mediated decay
Cellular component: cytoplasmic ribonucleoprotein granule; nucleus; P-body; RISC complex; cytosol; RNA decapping complex
Genetic constraint (gnomAD): Loss-of-function variants: 30 observed, 51.31 expected, observed/expected ratio (o/e) 0.58, 90% interval 0.44 to 0.79. The upper end of that interval is the gene's LOEUF score, 0.79, which puts it in group 3 of 6, group 1 being the genes least tolerant of losing a copy. Missense variants: 504 observed, 487.98 expected, observed/expected ratio (o/e) 1.03, 90% interval 0.96 to 1.11. Synonymous variants: 187 observed, 157.95 expected, observed/expected ratio (o/e) 1.18, 90% interval 1.05 to 1.34.
Homologues: Orthologues: chimpanzee DCP2 (99% identical), macaque DCP2 (99% identical), dog DCP2 (97% identical), guinea pig DCP2 (95% identical), rat Dcp2 (93% identical), mouse Dcp2 (93% identical), pig DCP2 (93% identical), rabbit DCP2 (91% identical), tropical clawed frog dcp2 (70% identical), zebrafish dcp2 (68% identical), Drosophila melanogaster DCP2 (39% identical), Caenorhabditis elegans dcap-2 (35% identical).
Diseases named in the same sentence as DCP2 in open-access papers:
DCP2 is named in the same sentence as 17 diseases in open-access papers, as found by Europe PMC text mining. Sharing a sentence is not in itself a finding about the gene and the disease. The quoted sentences say what the papers report.
small cell lung carcinoma (5 papers, 2024 to 2025). Small cell lung cancer (SCLC) is a highly aggressive malignant neoplasm, accounting for 10-15% of lung cancer cases, characterized byrapid growth, and early metastasis. "METTL3-mediated m6A modification of uncapped mRNA2235 (DCP2) triggers its degradation, and promotes mitosis and chemoresistance in small cell lung cancer (SCLC) cells through the PINK1/Parkin pathway." (PMID 40786181, 2025). "In small cell lung cancer, METTL3 induces m6A methylation of DCP2, leading to DCP2 degradation and promoting mitochondrial autophagy through the Pink1-Parkin pathway." (PMID 39289775, 2024). "METTL3 induces the degradation of decapping protein 2 (DCP2), resulting in reduced inhibition of PINK1 and Parkin with enhanced mitophagy, alleviated tumor cell dysfunction levels and increased chemotherapy resistance in small cell lung cancer (SCLC)." (PMID 41373022, 2025). "Moreover, METTL3 enhanced chemotherapy resistance in small cell lung cancer (SCLC) by activating the Pink1–Parkin mitophagy pathway and exacerbating mitochondrial damage through DCP2 targeting." (PMID 41142801, 2025).
lung carcinoma (4 papers, 2020 to 2022). "Recent study founded that miR-4293 can promote the proliferation of lung carcinoma by targeting DCP2, which is a mRNA-decapping enzyme." (PMID 36339001, 2022). "In this study, we found that miR-4293 downregulates the degradation of WFDC21P by directly mediating DCP2, which plays important role in the tumorigenesis of lung carcinoma." (PMID 34301920, 2021). "We further clarified that WFDC21P downregulation played important role in the tumorigenesis of lung carcinoma, and showed that DCP2 regulated by miR-4293, downregulated WFDC21P expression." (PMID 34301920, 2021). "In this study, we presented evidence that DCP2 is a target of miR-4293 and that miR-4293 is highly expressed in lung carcinoma tissue and promotes cell proliferation and migration, but inhibits apoptosis." (PMID 34301920, 2021). "In humans as well, chromosomal deletions of 5q21-22, the region harboring DCP2, is frequently observed in lung cancers, colorectal cancer and oral squamous cell carcinoma." (PMID 32591349, 2020). "Therefore, we assumed that WFDC21P may be regulated by DCP2, and is involved in the pathogenesis of lung cancer." (PMID 34301920, 2021).
viral infection (3 papers, 2015 to 2024). "SF3B1 could be a potential biomarker for cervical cancer, while DCP2 may serve as a viral infection indicator." (PMID 38790189, 2024). "Meanwhile, DCP2 and decapping machinery may also contribute to innate immune response by a negative feedback mechanism to restore normal homeostasis following viral infection." (PMID 26431425, 2015). "Importantly, these mutants are not postembryonic lethal, in contrast to null mutants of DCP1, DCP2, and VCS, and grow well enough for virus infection experiments." (PMID 35511183, 2022).
liver disease (1 paper, 2025). "Interestingly, many of the genes linked to the differentially methylated CpGs have been associated with liver disease progression (eg, DCP2, TRPV3, ARRB1, KCNIP4, MIR10A) and cancer formation or progression (eg, MTHFR, GRIK2, GSN, HOX3, KCNMA1)." (PMID 40275933, 2025).
nicotine dependence (1 paper, 2012). Physical and psychological dependence on nicotine. "Our findings reveal a significant role for the mRNA decapping pathway in developing locomotor hyperactivity in response to chronic nicotine exposure and identify Dcp2 as a potential candidate for future research on nicotine dependence." (PMID 23300696, 2012).
ovarian carcinoma (1 paper, 2025). A malignant neoplasm originating from the surface ovarian epithelium. "We also found that high expression of DCP2 in ovarian cancer tissue is associated with poor patient prognosis." (PMID 40895564, 2025). "In this study, we found through CCK8 and plate cloning experiments that DCP2 promotes ovarian cancer cell proliferation, and through transwell experiments, we found that DCP2 promotes ovarian cancer cell metastasis." (PMID 40895564, 2025). "The risk score constructed based on DCP2 and NUDT16 is an independent prognostic factor for ovarian cancer, suggesting the important functions of these two genes in ovarian cancer, which undoubtedly deserves further study." (PMID 40895564, 2025). "The flat panel cloning method visually shows that the number of clonogenic cells from ovarian cancer cells knocked down by DCP2 is smaller than that of the control group, while the clonogenic ability of cells knocked down by NUDT16 is diminished." (PMID 40895564, 2025). "Further analysis showed that two m7g regulator genes, DCP2 and NUDT16, could be used to construct a prognostic risk model of ovarian cancer, and that risk scores were significantly associated with ovarian cancer prognosis." (PMID 40895564, 2025). "m7G modification affects the cellular composition of the immune microenvironment in ovarian cancer, and two key m7G modification-regulated genes, DCP2 and NUDT16, promotes the proliferation and metastases of ovarian cancer cells, and its high expression is associated with poor prognosis." (PMID 40895564, 2025). "However, there is no research reports on the specific function of DCP2 in ovarian cancer." (PMID 40895564, 2025).
tumor (10 papers, 2019 to 2025). "Other research shows that miR-4293 regulating WFDC21P through downregulate DCP-2 while miR-4293 promotes tumor cell proliferation and metastasis but suppresses apoptosis." (PMID 40895564, 2025). "We also analysed DCP2 expression in subcutaneously transplanted nude mouse tumours in which we knocked down or overexpressed METTL3." (PMID 36932427, 2023). "In our study, we found high expression of EIF4E1B, LARP1, GEMIN5, and DCP2 in tumor tissues, which seems to be consistent with our results." (PMID 36003341, 2022). "For example, decapping enzyme Nudt3, a member of nudix hydrolase superfamily, promoting MCF7 cell migration and proliferation by modulating β6 and lipocalin-2 mRNA stability; Dcp2, the first discovered decapping enzyme, enhanced tumor cell growth by affected RAS and MYC mRNA stability." (PMID 31164795, 2019). "Notably, DCPS manifested pronounced expression in both neoplastic and non‐neoplastic tissues, while DCP2, NCBP2, WDR4, and NUDT3 demonstrated intermediate expression across tumor and normal samples." (PMID 40485623, 2025). "This translocation of DCP1A/DCP2 also leads to disassembly of P-bodies; thus, PNRC1 could also inhibit tumor cell proliferation by disrupting P-body formation." (PMID 39046443, 2024). "However, there were a few downregulated genes in tumor samples, such as CYFIP1, IFIT5, DCP2, and EIF4E3." (PMID 36761423, 2022). "There are no prior reports on whether DCP2 is involved in tumour drug resistance." (PMID 36932427, 2023).
cancer (7 papers, 2021 to 2025). A tumor composed of atypical neoplastic, often pleomorphic cells that invade other tissues. "The downregulation of lncRNAs mediated by DCP2 may become a novel underlying mechanism of lncRNAs in different kinds of carcinoma." (PMID 34301920, 2021). "For example, hsa-miR-224 which targeting DCP2 was up-expressed in 10 cancers, while down-expressed only in 1 cancer." (PMID 36339001, 2022). "By decapping a subset of mRNAs, DCP2 plays an important role in cancer pathogenesis by affecting processes such as cell migration and apoptosis." (PMID 34301920, 2021). "Overall, our results establish oncogenic roles for both miR-4293 and WFDC21P and demonstrate that interactions between miRNAs and lncRNAs through DCP2 are important in the regulation of carcinoma pathogenesis." (PMID 34301920, 2021). "DCP2 is involved in the pathogenesis of some carcinoma by degrading RNA." (PMID 34301920, 2021). "Accordingly, we observed that DCP2 can bind to WFDC21P, a long non-coding RNA, to participate in cancer pathogenesis." (PMID 34301920, 2021). "Next, we added NuRD complex as a new molecule and ran the “Path Explorer” tool between SET A (NuRD) and SET B (SF3B1B, PHF6, EIF4G3, DCP2, GPR15, miR-490, LINC01222, LINC01718, LINC02036) with the same parameters for diseases: “Cancer”, “Infectious Disease”, and “Reproductive Disease System”." (PMID 38790189, 2024). "However, more regulator genes negatively related to those compounds, like AGO2, DCP2, EIF3D, EIF4E, LARP1, and NCBP3 (related to 30 cancer drugs both in GDSC and CTRP), indicating the patients with higher mRNA expression level of these regulator genes might sensitive to these compounds." (PMID 36092891, 2022).
infection (5 papers, 2018 to 2025). The state of being infected such as from the introduction of a foreign agent such as serum, vaccine, antigenic substance or organism. "Dcp2 restricts RVFV infection in Drosophila by decapping mRNAs preferentially targeted by RVFV cap-snatching, such as those related to cell cycle." (PMID 36078091, 2022). "We further assessed the expression in a later point of infection (24 h) of three targets of miR-217 during OROV infection: DCP2, MAPK1 and SIRT1." (PMID 29813068, 2018). "In our model, DCP2 kept a decreasing expression in infected cells, being 20 fold significantly down-regulated at 24 h post infection (p ≤ 0.001)." (PMID 29813068, 2018). "Nonetheless, the predicted target genes for miR-217 and miR-576-3p, DCP2 and STING, respectively, recovered to similar levels to non-infected cells in the presence of miRNA inhibitors 18 h post-infection." (PMID 29813068, 2018). "To evaluate whether EBOV replication depends on decapping components other than EDC4, we tested the impact of knockdowns of DCP1A, B and DCP2 and accessory decapping protein EDC3 on infection efficiency." (PMID 41006235, 2025). "Although not proved as a miRNA target yet, we included DCP2, the only selected miR-217 target already significantly down-regulated at 12 h post infection, because of its relevance as a restriction factor for other bunyavirus." (PMID 29813068, 2018). "The transcript levels were consistently elevated for DCP1, DCP2, and more strongly for VCS with both CaMV strains, while DCP5 expression was only induced during Cabb B-JI infection, and LSM1a expression was not responsive to either strain (Figure�1D)." (PMID 35511183, 2022).
DCP2 also shares sentences with these, for which no sentence is quoted: colorectal cancer (2 papers); cervical cancer (1); glioma (1); infectious disease (1); liver fibrosis (1); melanoma (1); oral squamous cell carcinoma (1); Reproductive Disease (1).